OGT (O-linked N-acetylglucosamine (GlcNAc) transferase)
Diseases named in the same sentence as OGT in open-access papers (continued):
Sharing a sentence is not in itself a finding about the gene and the disease.
hyperlipidemia (1 paper, 2022). "These connections provide plausible paths by which hyperlipidemia may influence the protein expression or activity of OGT and OGA." (PMID 36111295, 2022). "Therefore, increased macrophage OGT activity during a transient period of hyperlipidemia is likely protective against excessive inflammation and may stimulate negative feedback on overeating." (PMID 36111295, 2022). "Protein O-GlcNAcylation has not been directly linked to enterocyte physiology but OGT and sOGA activity in other cell types regulate the stability and activity of CD36 and PLIN2, which are central to hyperlipidemia adaptations in the intestine." (PMID 36111295, 2022).
idiopathic pulmonary arterial hypertension (1 paper, 2024). A sporadic form of pulmonary arterial hypertension (PAH) characterized by elevated pulmonary arterial resistance leading to right heart failure. "We have previously reported that OGT/O-GlcNAc regulates pulmonary arterial smooth muscle cell proliferation and vascular angiogenesis in idiopathic pulmonary arterial hypertension (IPAH)." (PMID 38665916, 2024).
laminopathies (1 paper, 2025). "For the M1014V OGT variant, a concurrent missense mutation was identified in LMNA (LMNA-R545H), a gene encoding A-type lamins associated with laminopathies and, in this case, ID." (PMID 39706180, 2025).
mesenchymal tumors (1 paper, 2021). "Our findings extend the spectrum of mesenchymal tumors involving members of the FOXO family of transcription factors and point to the existence of a family of soft tissue tumors that carry the gene fusion of the OGT-FOXO family." (PMID 33506328, 2021).
mesothelioma (1 paper, 2024). A usually malignant and aggressive neoplasm of the mesothelium which is often associated with exposure to asbestos. "BAP1 mediates the poly-deubiquitination of OGT to prevent its proteasomal degradation in NCI-H226 mesothelioma cells." (PMID 39715739, 2024).
mood disorder (1 paper, 2023). A cognitive disorder a disturbance in which the person's mood is hypothesized to be the main underlying feature. "However, the central role of OGT in stress and mood disorders is still unclear." (PMID 36757814, 2023).
myelodysplastic syndrome (1 paper, 2021). A clonal hematopoietic disorder characterized by dysplasia and ineffective hematopoiesis in one or more of the hematopoietic cell lines. "In myeloid malignancies, OGT directly stabilizes ASXL1 by O-GlcNAcylation and drives myeloid differentiation associated with the pathogenesis of myelodysplastic syndrome (MDS)." (PMID 33726758, 2021).
myocardial ischemia (1 paper, 2024). A disorder of cardiac function caused by insufficient blood flow to the muscle tissue of the heart. "Meanwhile, we have confirmed in previous studies that OGT-mediated O-GlcNAcylation plays a crucial role in myocardial ischemia–reperfusion injury." (PMID 38778315, 2024). "In summary, MTH activates OGT mediated O-glycosylation modified COX10 to regulate mitochondrial function and improve myocardial ischemia–reperfusion injury, which provides important theoretical basis for the clinical application of MTH." (PMID 38778315, 2024).
osteoporosis (1 paper, 2023). A condition of reduced bone mass, with decreased cortical thickness and a decrease in the number and size of the trabeculae of cancellous bone (but normal chemical composition), resulting in increased fracture incidence. "While this study primarily focused early life bone development, it is warranted to further investigate the role of OGT in the transition to appositional remodeling during adulthood and in osteoporosis pathogenesis during aging." (PMID 36861967, 2023).
pancreatic adenocarcinoma (1 paper, 2019). "In numerous human cancers, particularly in pancreatic adenocarcinoma, OGT and OGA expression levels are highly positively correlated." (PMID 31272438, 2019).
placental insufficiency (1 paper, 2021). Failure of the placenta to deliver an adequate supply of nutrients and oxygen to the fetus. "Placental O-GlcNAc transferase (OGT) has been identified as a marker and a mediator of placental insufficiency in the setting of prenatal stress, however, its role in the fetal programming of metabolism and glucose homeostasis remains unknown." (PMID 34203166, 2021). "The investigation into placental OGT could provide a greater understanding of fetal metabolic programming and identify potential therapeutic targets to improve fetal outcomes and mitigate the long-term metabolic consequences for offspring of gestational diabetes and placental insufficiency." (PMID 34203166, 2021).
progeria (1 paper, 2018). "We found that progeria-associated deletions either abolished (Δ50) or greatly reduced (Δ35) lamin A modification by OGT in vitro." (PMID 29772801, 2018). "Collectively, our findings provide novel insight into progeria mechanisms by predicting a second molecular consequence of the ∆50 deletion: loss of OGT-dependent regulation." (PMID 29772801, 2018). "Our results suggest OGT-dependent control of lamin A is perturbed by progeria-associated deletions." (PMID 29772801, 2018). "We conclude that residues deleted in progeria are required for substrate recognition and/or modification by OGT in vitro." (PMID 29772801, 2018). "We report extensive O-GlcNAc modification of residues unique to lamin A in vitro, and evidence that lamin A substrate recognition or modification by OGT requires residues deleted in progeria." (PMID 29772801, 2018).
prostate tumor (1 paper, 2014). "Another study using prostate tumor cells LNCaP siRNA-mediated OGT knockdown also decreased tumor cell invasion when compared with control siRNA-transfected cells." (PMID 24918087, 2014). "OGT knockdown in the PC3-ML prostate tumor cell line also reduced their ability to migrate when compared with control cells." (PMID 24918087, 2014). "The OGT knockdown of prostate tumor cells showed marked reductions of FoxM1 protein levels." (PMID 24918087, 2014). "With respect to tumor progression, the authors searched the National Center for Biotechnology Information (NCBI) database and found a positive correlation between high OGT expression and metastatic progression in normal, primary tumor, and metastatic prostate tumor tissues." (PMID 24918087, 2014). "Moreover, Lynch and co-workers injected into mice highly bone metastatic prostate tumor cells (PC3-ML), silenced or not for OGT; after 5 weeks, animals injected with OGT knockdown cells had fourfold less bone metastases to mandibles and hind limbs." (PMID 24918087, 2014).
pulmonary hypertension (1 paper, 2021). Increased pressure within the pulmonary circulation due to lung or heart disorder. "Taken together, these data suggest that increased OGT expression and activity contributes to the development of pulmonary hypertension by altering protein function through O-GlcNAc modifications, which are distinct from its effects on ROS production." (PMID 34068984, 2021).
skin inflammation (1 paper, 2019). "Remarkably, the Foxp3YFP-Cre/YOgtfl/YRosa26Stat5b-CA/wt mice with STAT5B-CA overexpression specifically in OGT-deficient Treg cells alleviated skin inflammation, reduced sizes of the LNs and spleen, and prolonged lifespan, when compared to Foxp3YFP-Cre/YOgtfl/Y mice." (PMID 30664665, 2019).
sleep disorder (1 paper, 2024). A change from the patient's baseline sleeping pattern, in the hours slept and/or an alteration/dysfunction in the stages of sleep. "Future studies investigating the regulatory mechanisms governing HBP flux during sleep cycles, as well as the cyclic patterns of OGA and OGT expression, will be crucial in unraveling the association between sleep disorders and the development of AD." (PMID 39044290, 2024).
small cell lung carcinoma (1 paper, 2024). Small cell lung cancer (SCLC) is a highly aggressive malignant neoplasm, accounting for 10-15% of lung cancer cases, characterized byrapid growth, and early metastasis. "OGT is a potential therapeutic target for some cancers, including small-cell lung cancer." (PMID 38213773, 2024).
squamous cell carcinoma of lung (1 paper, 2021). "The Cancer Genome Atlas datasets show the aberrant levels of OGT in both adenocarcinoma and squamous cell carcinoma of lung." (PMID 34771527, 2021).
tauopathy (1 paper, 2020). Neurodegenerative disorders involving deposition of abnormal tau protein isoforms (tau proteins) in neurons and glial cells in the brain. "It has been reported that the modulation of O-GlcNAcylation levels by azaserine or glucosamine or by overexpression of OGT or OGA plays an important role in regulating the toxicity of mutant huntingtin in the cellular model of tauopathy and Drosophila." (PMID 33317171, 2020).
thyroid anaplastic cancer (1 paper, 2018). "It has been shown that elevation of O-GlcNAcylation by OGA inhibition or overexpression of OGT could increase Akt phosphorylation at Ser-473 in thyroid anaplastic cancer cells." (PMID 29915392, 2018).
thyroid cancer (1 paper, 2023). "Elevated levels of OGT and O-GlcNAc in thyroid cancer cells are also associated with increased invasion and migration capacity of cancer cells." (PMID 37838167, 2023). "Inhibition of OGT in thyroid cancer cells notably reduces invasion, migration, and metastasis ability of thyroid cancer cells." (PMID 37838167, 2023).
tongue squamous cell carcinoma (1 paper, 2015). A squamous cell carcinoma that arises from the tongue. "To analyze whether the role of autophagy affecting the glycosylation in tongue squamous cell carcinoma is dependent on the variation of the hypoxia, we designed the OGT protein detected based on the autophagy knockdown while HIF-1α was inhibited." (PMID 26640316, 2015).
α-synucleinopathies (1 paper, 2025). "Pharmacological inhibition of OGA or OGT effectively alleviates or exacerbates α-syn aggregation, spreading, dopaminergic neuron degeneration, and neuroinflammation, which contribute to α-synucleinopathies in neurodegenerative diseases." (PMID 41146299, 2025).
cancer (192 papers, 2009 to 2026). A tumor composed of atypical neoplastic, often pleomorphic cells that invade other tissues. "Prior studies linked OGT to cancer metastasis via autophagy and ferroptosis regulation, suggesting O-GlcNAcylation modulation as a therapeutic avenue." (PMID 41301681, 2025). "It has been observed that higher levels of O-GlcNAcylation and OGT in cancer patients are associated with cancer progression and a poor prognosis." (PMID 38773637, 2024). "Other reports have shown that altered levels of O-GlcNAc and OGT are associated with the promotion of resistance to anti-cancer therapeutic agents." (PMID 39337387, 2024). "We first analyzed gene expression profiles of cancer patients from TCGA database and survival, we found that low OGT expression was associated with improved overall survival (OS) and progression free survival (PFS) in patients with COAD." (PMID 38168435, 2024). "Mass spectrometry analyses showed that FBP1 bound to O-linked N-acetylglucosamine (GlcNAc) transferase (OGT), which is frequently overexpressed in many types of cancer including HCC tissues." (PMID 36857532, 2023). "In humans, high OGT levels in TAMs are linked to cathepsin B expression, predicting chemotherapy results and cancer outcomes." (PMID 38116061, 2023). "OGT expression was also associated with infiltration levels of B cells and neutrophils in some/all of the three cancers." (PMID 35356257, 2022). "Together with an increase in UDP-GlcNAc synthesis, OGT overexpression in cancer cells causes aberrant hyper-O-GlcNAcylation." (PMID 35740678, 2022). "Despite these propitious findings, only a few systematic analyses of OGT/OGA-associated PPI networks have been reported in cancer models." (PMID 36291918, 2022). "In our study, we investigated the expression, clinical relevance, and underlying mechanisms of OGT in pan-cancer, including SCLC." (PMID 35356257, 2022). "The profiling of OGT/OGA-associated PPIs in cancer cells typically apply affinity purification or proximity biotinylation coupled with quantitative LC-MS/MS analysis (AP-MS or BioID-MS)." (PMID 36291918, 2022). "For instance, upregulated OGT and O-GlcNAcylation are intimately associated with nearly every cancer-related phenotype, ranging from cell proliferation, epithelial–mesenchymal transformation (EMT), angiogenesis, to metastasis." (PMID 36291918, 2022). "Aberrant OGT expression was identified and demonstrated significant associations in multiple cancers." (PMID 35356257, 2022). "O-GlcNAc modification of c-Myc protein by O-linked β-N-acetylglucosamine transferase (OGT) can stabilize c-Myc protein in cancer cells." (PMID 35308201, 2022). "Elevated glucose flux through the abnormal upregulation of O-linked β-N-acetylglucosamine (O-GlcNAc) transferase (OGT) controls key signaling and metabolic pathways regulating diverse cancer cell phenotypes." (PMID 35625898, 2022). "The Spearman correlation analysis and enrichment analysis were utilized to explore the underlying mechanisms of OGT in cancers." (PMID 35356257, 2022). "Levels of O-GlcNAc transferase (OGT) and hyper-O-GlcNAcylation expression levels are associated with cancer pathogenesis." (PMID 34681736, 2021). "Imbalanced levels of OGT and O-GlcNAcylation is a hallmark of various cancers, and these imbalances play a role in promoting metastatic disease." (PMID 34680309, 2021). "In the future, novel mechanisms underlying the dysregulation of HBP enzymes and OGT/OGA will likely be identified in cancer as well." (PMID 35201498, 2021). "This study shows that OGT is a substrate of the E3 ubiquitin ligase X-linked inhibitor of apoptosis (XIAP) which plays an important role in cancer pathogenesis." (PMID 32994395, 2020).
cancer (continued). "O-GlcNAc Transferase (OGT) is a complementary enzyme that regulates O-linked N-acetylglucosaminylation(O-GlcNAcylation) and plays a critical role in various cancer phenotypes, including invasion, migration, and metabolic reprogramming." (PMID 33251387, 2020). "Dysregulation of O‐GlcNAcylation in response to high glucose or OGT expression has been implicated in metabolic diseases and cancer." (PMID 30677218, 2019). "Cancer progression is often associated with an increase in surface N-glycans, and, on the other hand, OGT and O-GlcNAcylation are known to be up-regulated in carcinogenesis." (PMID 30400201, 2018). "O-linked N-acetylglucosamine transferase (OGT) expression is increased in various cancer types, indicating the potential importance of O-GlcNAcylation in tumorigenesis." (PMID 29435130, 2018). "The O-GlcNAcylation elevation observed in cancer cells seems also to be caused by an increased OGT expression." (PMID 26835421, 2016). "OGT provides a link between metabolism and histone H2B O-GlcNAcylation and has recently been implicated in the aberrant epigenetics of cancer." (PMID 25985759, 2015). "DNA methylation enzymes of the Tet family, involved epigenetic alterations associated with cancer, were recently found to interact with and target OGT to multi-molecular chromatin-remodeling complexes." (PMID 23964270, 2013). "By combining population datasets with cancer mutation databases, we identify distinct hotspot mutations with opposing clinical associations: OGT hotspot mutations correlate with improved survival in cancer patients, whereas OGA hotspot mutations are associated with reduced overall survival." (PMID 42107645, 2026). "Recent data implicated OGT as a key molecule for tumour metastasis and chemoresistance, such as with breast and ovarian cancer." (PMID 38213773, 2024). "Targeting the enzymes linked to O-GlcNAcylation and ubiquitination, such as OGT and ubiquitin-specific proteases, respectively, may help overcome resistance to cancer therapies." (PMID 39487556, 2024). "Recent studies have linked OGT/O-GlcNAc signaling to CSCs properties in various cancers." (PMID 37152043, 2023). "Interestingly, decreased OGA and/or increased OGT and O-GlcNAcylation levels are associated with poor cancer grade progression." (PMID 36059648, 2022). "Furthermore, OGA with point mutations in the pHAT domain showed aberrant protein interactions compared to wild-type OGA (see “Systematic analyses of OGT/OGA associated PPI networks in cancer” section below)." (PMID 36291918, 2022). "OGT may be an underlying biomarker for the treatment and identification of some cancers, including SCLC." (PMID 35356257, 2022). "For the first time in this study, it was revealed that SMAD4, a major regulator of TGF-β signaling preceding cancer EMT and metastasis in advanced cancers, was a target for O-GlcNAcylation and that O-phosphorylation is interrupted during hyper-O-GlcNAcylation caused by OGT overexpression." (PMID 33199824, 2020). "Increased levels of OGT or USP7 are associated with human cancers." (PMID 26678539, 2015). "As is the case with FASN, OGT is highly expressed in a large variety of cancers where it contributes to the processes of carcinogenesis." (PMID 41550490, 2026). "Because of their pro-oncogenic activities, defining the respective domains of FASN and OGT that drive their interaction is of special interest so as to be able to propose novel therapeutic avenues for cancer treatment, especially hepatocarcinomas." (PMID 41550490, 2026). "OGT activity and O‐GlcNAcylation are increased in most malignant tumors and correlate positively with tumor progression and recurrence." (PMID 40237201, 2025). "The process of O-GlcNAcylation and its enzyme OGT function to couple metabolism to signaling transduction in cancer cells." (PMID 40136647, 2025). "Both O-GlcNAcylation and its enzyme O-GlcNAc transferase (OGT) are highly expressed in many cancers, where it promotes tumor growth and metastasis." (PMID 40136647, 2025).